RN7SL110P (RNA, 7SL, cytoplasmic 110, pseudogene)
Gene: Miscellaneous RNA gene on chromosome 3 (15,506,623 to 15,506,905, reverse strand). Ensembl gene ENSG00000241064.
Homologues: Orthologues: chimpanzee Metazoa_SRP (98% identical), macaque Metazoa_SRP (92% identical). Paralogues in human: RN7SL1 (81% identical), RN7SL3 (81% identical), RN7SL2 (80% identical), RN7SL711P (79% identical), RN7SL15P (78% identical), RN7SL18P (78% identical), RN7SL451P (78% identical), RN7SL655P (78% identical), RN7SL220P (77% identical), RN7SL797P (77% identical), RN7SL126P (77% identical), RN7SL398P (77% identical), and 700 more.